SHH (sonic hedgehog signaling molecule)
Diseases named in the same sentence as SHH in open-access papers (continued):
Sharing a sentence is not in itself a finding about the gene and the disease.
tumor (continued). "The sonic hedgehog (SHH) signaling pathway, first identified in Drosophila melanogaster, is implicated in normal organ development and homeostasis, stem cell maintenance and proliferation in vertebrates and may therefore be a candidate for the mechanism behind surviving tumor cell growth." (PMID 23762282, 2013). "In essence, there is an abundance of current literature suggesting a role for SHH in tumor cell growth, and our experiments support that SHH signaling is important in the pathway of dying cell stimulated tumor growth." (PMID 23762282, 2013). "Even though mutations of the SHH target gene, Glioma-associated oncogene homolog-1 (GLI1), are uncommon, approximately 90% of sporadic BCC overexpress GLI1, which contributes to tumor growth." (PMID 23284750, 2012). "In situ hybridisation on human ACP sections (n = 5) showed a pattern of SHH expression characterised by the presence of cell clusters analogous to the typical β-catnc cell clusters observed in these human tumours." (PMID 22349813, 2012). "Angiogenesis, which plays a critical role during tumor development, is tightly regulated by the Sonic Hedgehog (SHH) pathway, which has been known to malfunction in many types of cancer." (PMID 22949805, 2012). "Tumor angiogenesis is regulated by multiple cellular signaling pathways including Sonic Hedgehog (SHH) transduction cascade." (PMID 22949805, 2012). "In these tumours, SHH is released to the stroma (paracrine action) where it promotes tumour growth, infiltration and angiogenesis." (PMID 22349813, 2012). "Natural and synthetic Smoothened antagonists such as cyclopamine and IPI-926, respectively have inhibited proliferation, survival and have anti-tumor functions, resulting in abrogation of SHH signaling." (PMID 22087285, 2011). "Sonic Hedgehog (SHH) signaling is important in embryonic cell development and proliferation and aberrant pathway activation can lead to tumor formation, tumor cell self-renewal and the development of metastatic disease." (PMID 21394230, 2011). "Next, we observed the effect of SHH pathway blocking on chemoresistance of tumorsphere cells in vitro and tumor response to drugs in vivo." (PMID 21394208, 2011). "As SHH signaling pathway has emerged as a crucial pathway in the pathogenesis of various tumor types, SHH inhibitors are currently being evaluated as potential anticancer drugs." (PMID 20015350, 2009). "Taken together, these data show that the inhibition of the SHH pathway decreases tumor cell growth essentially by affecting cell proliferation." (PMID 20015350, 2009). "By quantitative RT-PCR and immunoblot, we report that the SHH signaling pathway is constitutively reactivated in tumors independently of the von Hippel-Lindau (VHL) tumor suppressor gene expression which is inactivated in the majority of CRCC." (PMID 20015350, 2009). "Herein, we also showed that the treatment of human CRCC tumor-bearing nude mice with cyclopamine decreases tumor vascularization, indicating that the SHH pathway stimulates neoangiogenesis in human CRCC." (PMID 20015350, 2009). "Our previous studies had examined expression of SHH pathway genes in six matched benign and tumor patient samples where we have also examined Perlecan mRNA or protein expression." (PMID 16507112, 2006). "To test for a tumor cell complex containing both Perlecan and SHH we performed co-immunoprecipitation studies from the LNCaP series." (PMID 16507112, 2006). "In metastatic tumor cells increased SHH signaling correlates with the maintenance of Perlecan expression and more Perlecan-SHH complexes." (PMID 16507112, 2006).
tumor (continued). "In four common samples where we observe up-regulation of Perlecan in tumor tissue, we previously detected up-regulation of SHH, PTCH1 and GLI1 (patients 945, 1854, 921 and 1866) suggesting a complete functional pathway in these tumors." (PMID 16507112, 2006). "However, inhibiting the SHH/GLI1 pathway pharmacologically can counteract tumor-related angiogenesis." (PMID 41522355, 2026). "Inhibiting the SHH/GLI1 pathway suppresses tumor growth, primarily through reduced angiogenesis." (PMID 41522355, 2026). "Thus, it is easy to understand how impairment of the SHH pathway can contribute to the development of diseases, and particularly to the onset of neoplasms." (PMID 41465387, 2025). "SHh pathway activates PSCs to synthesise more tumour stroma." (PMID 41561521, 2025). "Of particular interest are small-sized AgNPs (5 nm), which have shown potent anti-tumor effects against the U-87MG line, including by increasing reactive oxygen species (ROS) production and inhibiting the Sonic Hedgehog (SHH) signaling pathway, which can lead to reduced tumor proliferation." (PMID 40574001, 2025). "While much is known about SHH signaling in isolated cancer cells, less is understood about how these pathways operate within the context of the tumor microenvironment-particularly in the presence of astrocytes, which are abundant in the brain and interact closely with tumor cells." (PMID 40894044, 2025). "Genes implicated in embryonic and organ development, including SHH, NEUROG3, and MAFA, were downregulated, while immune-related genes like CCL2 and HAVCR2 were upregulated, suggesting immune modulation and alterations within the tumour microenvironment." (PMID 40683913, 2025). "Immunofluorescence in liver-infiltrating tumor tissues showed that AAV-SHH or AAV-FGF4 successfully activated the positive feedback regulation between FGF4/SHH and GREM1 in macrophages (F4/80+), which contributed to an increase in CD206+F4/80+ macrophages and a decline in CD8+CD3+ T cells." (PMID 40849639, 2025). "Importantly, several studies identified SHH MB tumor-promoting activities of astrocytes via the induction of sustained hedgehog signaling." (PMID 39762313, 2025). "Notably, desmoplastic histology, typically associated with SHH‐activated tumours, was observed in WNT, Group 3 and Group 4 tumours." (PMID 41033792, 2025). "Third, inhibition of DNMT1 blocked SHH pathway output as supported by a previous study, and pathway inhibition as well as anti-tumor activity were also seen in the presence of genetic alterations within the SHH pathway previously shown to render tumors resistant to SMO inhibition." (PMID 39107797, 2024). "GBM cells secrete factors such as receptor activator of nuclear factor kappa beta ligand (RANKL) and sonic hedgehog (SHH) protein, activating nuclear factor kappa-light-chain-enhancer of activated B cells (NF-κB) signaling in astrocytes, thereby promoting tumor invasiveness." (PMID 38732975, 2024). "In PARD3-overexpressing CD133+ tumor-initiating cells, activation of SHH signaling was observed." (PMID 38730691, 2024). "Inhibition of SHH signaling may reduce the tumorigenicity of PARD3-overexpressing CD133+ tumor-initiating cells both in vivo and in vitro." (PMID 38730691, 2024). "This study aims to fill that knowledge gap by examining the key genes within the SHH pathway and how they might influence the survival, clinical features, and tumor characteristics of people affected by EC." (PMID 39408773, 2024). "Metastatic tumors retained abnormal SHH signaling as tumor xenografts." (PMID 38730706, 2024). "Advanced HNSCC tumours were shown to express higher levels of SHH, PTCH1, SMO, GLI1, GLI2 and GLI3." (PMID 39234399, 2024).
tumor (continued). "This suggests that targeting the SHH pathway could potentially enhance the effectiveness of radiotherapy by reducing radiation-induced DNA repair and tumor cell survival." (PMID 38730691, 2024). "However, our results revealed a significant decrease in SMO and GLI‐1 protein levels in tumor tissues, suggesting that Rab23 plays a negative regulatory role in the SHH signaling pathway and can suppress tumor growth in HCC." (PMID 37884351, 2024). "Additionally, tumor-associated astrocytes (TAAs) promote glioma invasion via signaling pathways including NF-κB, interleukin (IL)-6/JAK/STAT, and SHH signaling, facilitated by connexin 43 (Cx43)-mediated gap junction formation." (PMID 38732975, 2024). "The SHH pathway plays a regulatory role in cell proliferation and survival within these tumours." (PMID 39568072, 2024). "Similarly, in cancer stem-like cells, the activation of SHH signalling helps sustain their stemness properties, allowing them to self-renew and resist differentiation, thereby promoting tumour growth and heterogeneity." (PMID 38317186, 2024). "Combination treatment in vitro was significantly more effective in inhibiting tumor growth and SHH activation than either SMO and DNMT1 inhibitors alone, and this synergistic effect was seen in both murine and human cell models of SHH-MB sensitive to SMO inhibitors." (PMID 39107797, 2024). "However, SHH pathway inhibition can also decrease cytotoxic T lymphocytes within the tumor, alongside an increase in CD4+ T helper cells, resulting in no net change in overall CD3+ T cell infiltration." (PMID 39335494, 2024). "Next, we investigated the role of SALL4 on SHH-dependent tumor growth." (PMID 38062245, 2024). "The SHH pathway, essential for chondrogenesis and involved in cellular differentiation, growth, and tissue patterning during embryonic development, remains active in certain pathological conditions, including various tumours." (PMID 39568072, 2024). "This indicates that the SHH pathway's role in gliomagenesis may vary significantly depending on the tumour's anatomical location and cellular context." (PMID 39568072, 2024). "It is suggested that growth factors, including SHH, produced by tumor cells paracrinely induce Gli1 and Gli2 expressions in tumor vascular endothelial cells, and various angiocline factors produced by tumor vascular endothelial cells induce SHH and Gli1 in tumor cells." (PMID 37240209, 2023). "Additionally, miR-9, when upregulated, downregulates tumor suppressor gene PTCH1, which results in the activation of the SHH signaling pathway, thus reducing tumor cell death." (PMID 37371047, 2023). "In the face of this evidence, researchers have hypothesized that the SHH pathway promotes tumor growth, infiltration, and angiogenesis by the activation of transcription factors in palisade cells by autocrine and paracrine actions." (PMID 36748936, 2023). "All patients with either a WNT-activated or high-risk SHH-activated tumor were still alive and without progression at the end of the study period." (PMID 36920679, 2023). "Silmitasertib is a CK2 inhibitor which inhibits transcription factor GLI which is a terminal effector within the SHH pathway with hopes that this may prevent tumor proliferation." (PMID 37509034, 2023). "In a way, myCAFs exert tumor suppressor function partially through the SHH-SMO signaling pathway." (PMID 37784082, 2023). "These CAFs are considered tumor repressive, along with other CAFs exhibiting stem cell characteristics, inhibit tumor growth and the effects of regulatory T-cells, and proliferate in response to SHH signaling." (PMID 37046676, 2023). "Here, we demonstrated that acquired mutations in the SHH pathway occur only when CSCs, not bulk tumor cells, depend on SHH signaling." (PMID 36688010, 2022).
tumor (continued). "In both infiltrative and mixed BCCs, high SHH expression was found in the tumor tongues presented as admixtures of rounded nodules and nodules with irregular contours, and small irregular tongues of tumor cells embedded in the fibrous stroma." (PMID 36014865, 2022). "Considering the growing resistance to SHH inhibitors, the strong correlation of this signalling pathway with targetable immune checkpoints creates new perspectives for the combined therapy of tumours such as BCC." (PMID 36291078, 2022). "Furthermore, it was reported that tumor-derived SHH directly acts on TAMs to promote M2 polarization, mediated by the transcription factor Krüppel-like factor 4 (Klf4)." (PMID 35860588, 2022). "Moreover, SHH protein overexpression is negatively correlated with tumor differentiation and predicts poor prognostic outcomes in LSCC patients." (PMID 35433472, 2022). "However, when we correlated SHH expression, dichotomized according to the median value, with three tumor size groups, the highest expression was observed for T3, then for T1, and the lowest for the T2 group (data not presented)." (PMID 36294994, 2022). "SHH signaling exists in a variety of animals and plays a fundamental role in regulating accurate organization of the body plan, and its abnormal activation occurs in a variety of tumor cells." (PMID 35445092, 2022). "The categorization of this new type of tumor may lead to new therapeutic strategies, because they might be sensitive to SHH pathway inhibitors." (PMID 35387638, 2022). "Since both SETD7 and GLI1 mRNA levels were upregulated in A-549 cell line when compared to the non-malignant bronchial epithelial lung cell line BEAS-2B, it is likely that SETD7 activates the SHH signalling in LCa promoting tumour growth and metastasis in vitro and in vivo via GLI3 methylation." (PMID 35326563, 2022). "Some SHh inhibitors have been developed to delay tumor progression." (PMID 36517618, 2022). "Treatment of an SCLC patient-derived xenograft (PDX) cell line with recombinant rSHH or viral infection with SMO-M2 accelerated cell proliferation in culture, whereas pharmacologic inhibition, genetic knockdown, or depletion of SHH/IHH by a blocking antibody inhibited tumor cell proliferation." (PMID 36010600, 2022). "Since HHIP-AS1 overexpression is a hallmark in SHH-driven tumors, we investigated whether HHIP-AS1 expression was dependent on SHH signaling in tumor cells." (PMID 35831316, 2022). "This could be explained by a disproportionately smaller number of T3 tumors in our cohort or the fact that studies that have shown a positive correlation between SHH expression and tumor size primarily studied SHH mRNA expression." (PMID 36294994, 2022). "PTEN acts as a tumor suppressor and it also impacts SHH and PI3K pathways." (PMID 35538578, 2022). "Similarly, DNAH2, a member of an axonemal dynein complex, is involved in motile cilia that plays a vital role in human development and homeostasis and is among the primary cilium-related genes that are enriched in both SHH and Group 3 tumours." (PMID 35008416, 2022). "We found that BMP2, BMP4 and SHH were highly expressed in tumor, lung and colon." (PMID 35902550, 2022). "The TUNEL assay revealed that SHH exposure significantly suppressed tumor cell apoptosis." (PMID 35154464, 2022). "Thus, in addition to taking into account the level at which the SHH pathway is compromised when designing targeted therapy, intrinsic characteristics of the cell-of-origin preserved in the tumor should also be taken into consideration." (PMID 35535520, 2022). "We next investigated whether HHIP-AS1 was similarly overexpressed in other tumor entities with aberrant activation of the SHH signaling." (PMID 35831316, 2022). "Interestingly, when directly comparing SHH versus MYC tumor cells via DE analysis, we found some of these mid/hindbrain and PGCs predictor genes as significantly upregulated in the respective subgroups." (PMID 35318328, 2022).
tumor (continued). "Taken together, deletion of SHH or SMO commonly inhibits tumor growth." (PMID 35159011, 2022). "Indeed, NOTCH inhibition by IMR-1 rescued the cilia deficit by inducing multiciliated tumor cells, whereas SHH pathway inhibitors suppressed tumor cell proliferation." (PMID 35322202, 2022). "SHH was not only highly expressed in tumor cells, but also in many stroma cells, which could be the reason why BMP expression is high in EAC tumor tissues but low in EAC cell lines." (PMID 35902550, 2022). "For example, PTEN acts as a tumor suppressor and it also impacts SHH and PI3K." (PMID 35538578, 2022). "Therefore, we believe that our outstanding OS and PFS is due, in part, to the high prevalence of SHH-activated tumours in our cohort when compared to current literature." (PMID 34436037, 2021). "It has also been reported that the SHH signaling pathway could regulate self-renewal and proliferation of CSCs and enhance tumor invasiveness." (PMID 34424425, 2021). "Interestingly, when LNCaP-AI cells were grown as spheroids, a more biologically relevant model of tumor growth, SHH expression increased while PTCH1 and GLI1 remained unchanged." (PMID 34290270, 2021). "SHH could be one such molecule, as it has been demonstrated that SHH secreted by tumor cells acts on osteoblasts, which in turn release IL-6, to promote osteoclast differentiation." (PMID 33731701, 2021). "The metastasis of SHH subgroup happens at the same site of primary tumour." (PMID 34944941, 2021). "We hypothesize that SHH and Group 4 tumours share some signalling similarities in response to laminin that eventually induce the nodular phenotype." (PMID 33206391, 2021). "Moreover, other pathways, such as ERBB2 and SHH signaling, have also been shown to be related to tumor growth and proliferation." (PMID 35155179, 2021). "SHH signalling also induces aerobic glycolysis in CGCPs and tumour cells to support biosynthesis." (PMID 34195095, 2021). "We can argue that SHH-signaling is probably inhibited, based on our finding that miR205HG overexpression reduces cell proliferation, clonogenicity, and in vivo tumor growth: these results resemble previously reported phenotypes of SHH-signaling inhibition in cancer cells." (PMID 33916875, 2021). "We propose that Rack1‐mediated Gli1 signaling and cell cycle activation in MB tumor cells might be essential for SHH‐MB tumorigenesis." (PMID 34480519, 2021). "Some epithelial cancer tumors can trigger SHH signaling to the stroma which enhances tumor growth." (PMID 31979397, 2020). "The SHH signaling pathway is also activated in the cancer stem cells (CSC) of several neoplasms." (PMID 31979397, 2020). "This together supported that OSCC-derived SHH in microvesicles may modulate angiogenesis and vascular bed preparation of primary tumours and future metastatic sites." (PMID 32054041, 2020). "Though SHH is important in embryonic vessel formation, its role in tumor vasculature remains unclear." (PMID 31979397, 2020). "A second mechanism of uncontrolled activation of SHH signaling may arise through increased secretion of SHH ligand by tumor cells into the immediate surrounding area." (PMID 32957513, 2020). "Likewise, SHH expression was detected in the tumor epithelium of prostate cancer samples while GLI1 expression, was upregulated in the stromal compartment, again providing evidence of paracrine ligand-dependent signaling to facilitate cancer development." (PMID 32957513, 2020). "Tumor cells secrete the sonic hedgehog (SHH), and tumor-derived SHH drives TAM M2 polarization." (PMID 33365025, 2020).